LYVE1 (lymphatic vessel endothelial hyaluronan receptor 1)
Diseases named in the same sentence as LYVE1 in open-access papers (continued):
Sharing a sentence is not in itself a finding about the gene and the disease.
melanoma (32 papers, 2004 to 2025). A malignant, usually aggressive tumor composed of atypical, neoplastic melanocytes. "Overall, these results indicated that tumor cell retention, tumor cell proliferation or apoptosis and alterations of vascularization were not responsible for the reduced susceptibility of the liver to melanoma metastasis in Lyve-1-KO." (PMID 36496412, 2022). "In metastatic lesions significantly smaller portions of macrophages were LYVE-1+ compared to naevi and primary melanoma indicating a loss of LYVE-1+ TAM in higher melanoma stages." (PMID 29262593, 2017). "A combination of LMW-HA and LYVE-1 promoted the proliferation and migration of lymphatic endothelial cells, thereby promoting lymphangiogenesis, while proliferation of melanoma cells is inhibited by ectodomain of LYVE-1 that was shed from M2-like tumour-associated macrophages." (PMID 38791985, 2024). "Lyve-1 deficiency protected from hepatic melanoma metastasis in an orthotopic injection model." (PMID 36496412, 2022). "Similarly, we observed loss of LYVE-1 expression on PDPN+ vessels proximal to melanoma tumor nests." (PMID 38361951, 2024). "Our results identify an enhanced premetastatic hepatic immune microenvironment which might promote initial tumor cell rejection and consequently decreased hepatic melanoma colonization, as initial tumor cell retention in mice with Lyve-1 deficiency was unaltered." (PMID 36496412, 2022). "This localization pattern is consistent with observations in other models such as B16F1 melanoma, where LYVE-1+ macrophages have been found in the periphery." (PMID 38717149, 2024). "LYVE-1 and D2-40 are already known biomarkers that play an important role in facilitating evidence of melanoma cancer cells within vascular or lymphatic structures, also known as LVI." (PMID 36613587, 2022). "On the contrary, when B16F10 luc2 melanoma cells were inoculated in Lyve-1-KO and Ctrl mice by intrasplenic injection, liver colonization was significantly decreased (P = 0.0093)." (PMID 36496412, 2022). "Upregulation of genes involved in macrophage recruitment (Ccl2), cell adhesion and migration (Vcam1, Stab1, Lyve1), angiogenesis (Vegfa) and cell proliferation/survival (Igf1) all suggested a phenotype similar to TAMs of s.c. melanoma." (PMID 36241867, 2022). "When WT31 melanoma cells were injected i.v., sizes of hepatic metastases in general were smaller and only a trend towards smaller metastases in Lyve-1-KO was detected." (PMID 36496412, 2022). "In livers with established B16F10 luc2 melanoma metastases a significant difference in the numbers of Treg cells (P = 0.0368) and neutrophils (P = 0.0261) was found in livers of Lyve-1-KO in contrast to Ctrl." (PMID 36496412, 2022). "The immunofluorescence of VEGF-C overexpressing murine melanoma tissue sections showed that in treated tissues, LYVE1+ cells were organized more sporadically and less collectively as vessels as compared with untreated samples." (PMID 32708166, 2020). "First, we investigated the role of CYLD in the formation of lymphatic vessels via immunofluorescence staining on murine Tg(Grm1) Cyld+/+ and Cyld−/− melanoma tissues using LYVE-1, a specific lymphatic endothelial marker." (PMID 31591386, 2019). "At first, the growth of B16F1 melanoma transplant tumors in C57BL/6 Lyve-1 knockout mice was examined and compared to tumor growth in wild-type control mice." (PMID 29262593, 2017). "In a similar manner, cultivation of HT144 in U937 conditioned medium resulted in a significant inhibition of proliferation of the human melanoma cell line specifically in medium derived from U937 LYVE-1+ cells." (PMID 29262593, 2017). "The aim of this study was to specifically analyze the possible relevance of LYVE-1 expression on TAMs for melanoma growth." (PMID 29262593, 2017).
melanoma (continued). "As in Lyve-1-/- mice, the proliferation rate of the melanoma cells was increased; we are convinced that excessive production of sLYVE-1 from macrophages and lymphatic endothelial cells in wild-type mice is the reason for impaired early tumor growth." (PMID 29262593, 2017). "In B16-F1 melanoma tumors, LYVE-1 and F4/80 co-localized with lymphatic structures, suggesting that a subset of TAMs became part of the tumor lymphatic endothelium." (PMID 22946011, 2012). "For instance, TAMs that were positive for CD11b+ and F4/80+ as well as for LYVE-1 and stabilin-1 were found in B16-F1 melanoma and Rip1Tag2 insulinoma models." (PMID 22946011, 2012). "Two recent studies in melanoma (using the anti-LYVE-1) confirmed the presence of focal areas exhibiting intratumoral lymphatic proliferation." (PMID 20374665, 2010). "Lyve-1 deficiency controlled hepatic metastasis in a tumor cell-specific manner leading to reduced growth of hepatic metastases of melanoma, but not CRC." (PMID 36496412, 2022). "Although there were no significant changes in the number of CD4+ and CD8+ T cells in livers of Lyve-1 KO mice bearing established melanoma metastases, tumor-free livers of Lyve-1 KO mice showed significant increased numbers of CD4+ and CD8+ T cells, Treg cells and eosinophils." (PMID 36496412, 2022). "Therefore, the immune cell composition of the hepatic niche was characterized in tumor-free, premetastatic livers and livers with established hepatic melanoma metastases of both Lyve-1-KO and Ctrl mice." (PMID 36496412, 2022). "However, as Lyve-1-KO showed no signs of capillarization or alterations of angiocrine metabolic functions, this cannot explain reduced melanoma metastasis in Lyve-1-KO livers." (PMID 36496412, 2022). "Here, similar intensities were observed in both groups indicating that Lyve-1 deficiency did not impair initial tumor cell retention of B16F10 luc2 melanoma cells to the hepatic sinusoids." (PMID 36496412, 2022). "The reduction of hepatic metastatic foci of B16F10 luc2 and WT31 melanoma in Lyve-1-KO as compared to Ctrl was confirmed by a significant reduction of the total macroscopic and microscopic tumor area in Lyve-1-KO with B16F10 luc2 or WT31 metastases after spleen injection." (PMID 36496412, 2022). "Due to the decreased hepatic metastasis in two melanoma models and the increased premetastatic pro-inflammatory state in Lyve-1-KO, Lyve-1 might be an interesting therapeutic target to further boost therapy response to ICI." (PMID 36496412, 2022). "Besides, this was confirmed in a second melanoma model as Lyve-1-KO also showed reduced hepatic colonization after spleen injection of WT31 melanoma as compared to Ctrl mice (P = 0.0164)." (PMID 36496412, 2022). "Histological staining for Vegfr3 (Fig EV1B) and for the lymphatic markers Prox1 and Lyve1 confirmed the inhibitory effect of BO‐110 in tumor‐driven neolymphangiogenesis at the cutaneous melanomas or at distal organs (see lungs in Fig EV1C) of Vegfr3Luc‐GEMM mice." (PMID 34762341, 2021). "Interestingly, melanoma tissue of Cyld-knockout mice exhibits more LYVE-1 positive vessels than the control group, thus CYLD is involved in the process of lymph angiogenesis." (PMID 31591386, 2019). "Also, sequential immunohistological staining of two TMAs showed significantly lower numbers of LYVE-1+ TAMs in higher melanoma stages, which points towards a reduced local amplification and/or recruitment of these cells." (PMID 29262593, 2017). "Previously, our group has identified LYVE-1+ TAMs in murine and human melanoma." (PMID 29262593, 2017). "This is in line with our finding that the number of LYVE-1+ TAM decreases in higher human melanoma stages and that the early growth of B16 transplant tumors is enhanced in Lyve-1 knockout mice when compared to wild-type mice due to an increased melanoma cell proliferation." (PMID 29262593, 2017).
melanoma (continued). "Moreover, the effects of the clinically approved anticoagulants on the intra- and peritumoral lymphatic vessel density in primary melanoma were examined in tissue sections of the primary tumors by Lyve-1 immunofluorescence stainings." (PMID 27602496, 2016). "However, the percentages of Lyve1+ or CD32b+ intratumoral vessels were significantly higher in HCmel12 in comparison to the other melanoma metastases (Lyve1+: 59.9% ± 6.3; CD32b+: 9.2% ± 3.4) indicating a mixed sinusoidal and capillarized molecular phenotype in a minor fraction of HCmel12 vessels." (PMID 35109875, 2022). "To investigate the antimetastatic effect of MG in the melanoma mouse model, we harvested the right inguinal lymph node of the mice and performed immunohistochemistry with anticytokeratin (tumor cell-specific) and anti-LYVE-1 (lymphatic vessel-specific) antibodies." (PMID 36110191, 2022). "The liver specific effect of Lyve-1 on melanoma metastasis could be proven by the intravenous injection route of WT31 melanoma cells, as deficiency of Lyve-1 led to a significant protection against hepatic but not pulmonary melanoma colonization." (PMID 36496412, 2022). "Since metastatic spread correlated with LD, even in thin melanomas, these results indicate that patients whose biopsy has a high LYVE-1 count could be included in a more intensive follow-up schedule, or considered for adjuvant treatment, even if the MM is thin." (PMID 14760386, 2004). "We generated a lymphatic score for melanoma samples based on the relative expression levels of PDPN, LYVE1, and VEGFC28, and found that GPR182 expression significantly correlated with lymphatic score in melanoma." (PMID 35013216, 2022). "This was interesting since recruitment of CD11b+, F4/80+, LYVE-1+, STABILIN-1+ macrophages has been reported in a melanoma model." (PMID 36230610, 2022). "The use of highly specific and sensitive antibody biomarkers for melanoma (S-100, Mart-1), for cell proliferation (Ki-67, PCNA), and for lymphatic vessels (LYVE-1, D2-40) allowed a better assessment of LVI." (PMID 36613587, 2022). "In this study, we show a correlation between high CD147 expression levels and the number of lymphatic vessels expressing LYVE-1, Podoplanin, and VEGFR-3 in human melanoma lymph nodes." (PMID 34638342, 2021). "An immunofluorescence study was performed to evaluate the expression of the three main lymphangiogenesis markers, Podoplanin, LYVE-1 and VEGFR-3, on 16 resected human melanoma lymph node metastases harboring high or low CD147 expression." (PMID 34638342, 2021). "The sequential staining of these samples revealed that in all naevi samples LYVE-1+ macrophages were present, while only in 73.3 % of primary melanoma samples and in 72.4 % of the metastasis CD68/LYVE-1 double positive cells were spotted." (PMID 29262593, 2017). "We found that macrophage-derived shedded Lyve-1 was able to inhibit LMW-HA-dependent proliferation of human and murine melanoma cells, pointing towards a possible decoy receptor function of the shedded receptor." (PMID 29262593, 2017). "Ang-2 gene expression correlated with LYVE-1 expression in CMM, which indicated that Ang-2 might promote lymphangiogenesis and tumor progression in melanoma." (PMID 37519819, 2023). "We show that Lyve-1 influences tumor-specific hepatic metastasis of melanoma but not CRC without interfering with angiocrine organ functions of LSECs." (PMID 36496412, 2022). "The percentage of Ki67+ or Casp-3+ tumor cells did not significantly differ between hepatic melanoma metastases of Ctrl and Lyve-1-KO mice." (PMID 36496412, 2022). "As Lyve-1 can be involved in tumor cell adhesion in vitro, initial tumor cell retention was also assessed in vivo by bioluminescence imaging in Lyve-1-KO and Ctrl mice 90 min after intrasplenic injection of B16F10 luc2 melanoma cells." (PMID 36496412, 2022).
melanoma (continued). "By contrast to CD31 positive blood vasculature, amount of LYVE-1 positive lymph vasculature was not significantly influenced by EphB4 overexpression in the A375 melanoma model, perhaps because of the broad intertumoral variability in lymphatic vessel density." (PMID 29462967, 2018). "LMW-HA/Lyve-1 interaction is therefore a two-edged sword for tumors such as melanoma as on the one hand it promotes lymphangiogenesis and therefore lymphangiogenic metastasis; on the other hand it inhibits LMW-HA dependent melanoma cell proliferation." (PMID 29262593, 2017). "Tumor-bearing LNs double-stained with TRP-1 and LYVE-1 antibodies, showed invasion of TRP-1-positive melanoma cells into LNs and an increase in LYVE-1-positive sinuses in the medulla, regardless of invasive grade." (PMID 23031500, 2012). "This is in contrast to other studies which have shown the absence of LYVE-1 and podoplanin positive lymphatics in human ciliary body with melanoma without extraocular extension, although neo-lymphatic vessels can proliferate into malignant melanomas of the ciliary body with extraocular extension." (PMID 36163311, 2022). "Alterations in hepatic metastasis of melanoma but not CRC indicate that the anti-tumor immune response may be altered in Lyve-1-KO." (PMID 36496412, 2022). "Furthermore, it may be possible, using LYVE-1 immunohistochemistry, to identify which of the thicker melanomas are not going to metastasise." (PMID 14760386, 2004). "Hepatic metastasis of B16F10 luc2 and WT31 melanoma cells, but not MC38 CRC cells, was significantly reduced in Lyve-1-KO mice." (PMID 36496412, 2022).
lymph node metastasis (13 papers, 2005 to 2024). "Contrastingly, in lung cancer patients, reduced serum levels of LYVE-1 showed a significant association with lymph node metastases and distant metastases." (PMID 38791985, 2024). "Elevated LYVE-1 expression and the occurrence of lymphatic invasion are associated with the presence of lymph node metastasis in neuroblastoma." (PMID 38791985, 2024). "An increased LYVE-1 protein level is closely associated with key adverse risk factors and lymph node metastasis." (PMID 27505247, 2016). "LYVE1 (lymphatic vessel endothelial hyaluronan receptor-1) has been identified as a biomarker of lymphangiogenesis and lymph node metastasis in multiple cancers with poor prognoses." (PMID 33995379, 2021). "In previous studies, the marker LYVE-1 was established to show that a high number of lymphatic vessels is prognostic for lymph node metastasis and metastasis in general." (PMID 31591386, 2019). "Lymphatic vessels in tumours related to lymph node metastasis were analysed by immunostaining with antibodies against the lymphatic endothelial marker LYVE-1." (PMID 29752441, 2018). "Nonetheless, this study shows a strong relationship between LYVE-1 expression and lymphatic thromboembolism, which is considered the first stage of lymph node metastasis." (PMID 25141859, 2014). "LYVE-1/PCAB detected LVI in 25/67 cases (37.3%) and their presence was significantly associated with both lymph node metastasis (χ2=4.698, P=0.0248) and unfavourable overall survival (OS) (P=0.0453), while not relapse- free survival (RFS) (P=0.2948)." (PMID 16251871, 2005). "In addition to the well-documented CD44, RHAMM, TSG-6, HAPLN, HABP4, and VCAN also play a profound role in distant metastasis, while LYVE-1 is mainly involved in lymph node metastasis." (PMID 38791985, 2024). "Thus, the role of LYVE1 in PTC and its relationship with lymph node metastasis remains to be elucidated." (PMID 31803141, 2019). "The genes of three markers of lymphatic endothelial commitment and development (PDPN, LYVE-1 and SLP-76) were significantly overexpressed in tissues of MIBC patients showing positive lymphovascular invasion (LVI+), lymph node metastasis (Ln+) and tumor progression." (PMID 28423532, 2017).
lymphedema (12 papers, 2012 to 2025). Excess fluid collection in tissues, causing swelling. "We assessed the development of LYVE1-positive lymphatic vessels on the incision site, at which skin regeneration occurred, as well as inflammation and lymphedema at edematous sites, at which inflammatory cells accumulated." (PMID 39925433, 2025). "We found a striking depletion of the anti-inflammatory macrophages, i.e., the c6 LYVE1+ resident-like subpopulation, in the adipose tissues of lymphedema." (PMID 35725971, 2022). "In the tail lymphedema model in mice by removing lymphatic vessel-included tail dermis, LYVE1+SMA+ LECs emerged in regenerating lymphatic vessels during lymphedema-associated lymphangiogenesis." (PMID 35130955, 2022). "This demonstrated a statistically significant increase in the number and size of LYVE-1+ lymphatics in the dermis and subcutaneous tissue in the mouse lymphedema model (nota bene: all LYVE-1+ lymphatics in tails were detected in the dermis and subcutaneous tissue)." (PMID 40060910, 2025). "Here, using a surgical mouse model of secondary lymphedema, we demonstrated that targeting IGF1R signaling with linsitinib restricted both tissue swelling and pathological remodeling of LYVE-1+ lymphatics (i.e., initial and/or precollector lymphatics) during lymphedema development." (PMID 40060910, 2025). "In addition, the proportion of LYVE‐1+CD11b+ double‐positive cells in bone marrow was increased in response to lymphedema." (PMID 23130156, 2012). "Since the expression of CSF1 in ASCs was even significantly higher in lymphedema than in healthy controls, we reason that the mechanism underlying the depletion of macrophages, especially for the LYVE1+ macrophages, may not be due to pathological changes in ASCs." (PMID 35725971, 2022). "Western blot analysis revealed that two molecular markers of lymphedema vascular endothelial growth factor receptor 3 (VEGFR-3) and lymphatic vessel endothelial hyaluronan receptor 1 (LYVE-1) were upregulated in the mice with lymphedema compared with the control and sham-operated mice." (PMID 28232732, 2017). "With decreased lymphatic function, this mouse model presented tissue swelling and formation of edema occurred as consequences of abnormal lymphatic system and also exhibited typical expression patterns of lymphedema markers such as VEGFR-3, LYVE-1, and α-SMA, in addition to collagen accumulation." (PMID 28232732, 2017). "To check whether this lymphedema was present in KO animals not affected by anasarca, we studied the morphology of lymphatic vessels in the intestine staining them with the specific marker Lyve1, and no major differences were observed." (PMID 27445864, 2016). "There was a tendency of more but not significantly increases in the expression of VEGF‐C, LYVE‐1, podoplanin, PROX‐1 and FLT4 in the lymphedema group in comparison to the normal group, suggesting that lymphangiogenesis occurs when lymphatic injury, tissue injury or lymphedema presents." (PMID 36176614, 2022).
lung carcinoma (11 papers, 2014 to 2025). "The study by Nunomiya and colleagues showed that lung cancer patients with lower LYVE-1 levels have poorer prognoses than patients with higher LYVE-1 levels." (PMID 30081883, 2018). "The results of this study show that the Shh signaling pathway affects survival in lung cancer and suggest that Shh initiates lymph node metastasis via LYVE-1-dependent lymphangiogenesis." (PMID 25141859, 2014). "A recent study showed that LYVE-1 expressed on the lymphatic endothelium may be shed and subsequently released into the circulation, as well as that low levels of LYVE-1 are observed in larger lung cancer tumors with greater metastasis." (PMID 28569211, 2017). "A total of 6 genes (LYVE1, CLEC3B, FGA, AOC3, HYDIN, and HBB) exhibited differential expressions in the plasma of LUSC and the area of the lesion in lung cancer (including LUAD and LUSC)." (PMID 40496615, 2025). "Our mouse xenograft model revealed that ANGPTL2 overexpression promotes the upregulation of LYVE-1 and VEGF-A expression in lung cancer tissue." (PMID 36917086, 2023). "In current report, we found higher levels of ANGPTL2 and LYVE-1 (a LEC marker) expression in lung cancer tissue than in normal control tissue." (PMID 36917086, 2023). "Interestingly, LYVE-1-positive lymphatic vessels appear to be present only on the periphery of endometrial and lung cancers, but not in solid tumours." (PMID 38791985, 2024).